TERF2IP (TERF2 interacting protein)
Description:
Acts both as a regulator of telomere function and as a transcription regulator. Involved in the regulation of telomere length and protection as a component of the shelterin complex (telosome). In contrast to other components of the shelterin complex, it is dispensible for telomere capping and does not participate in the protection of telomeres against non-homologous end-joining (NHEJ)- mediated repair. Instead, it is required to negatively regulate telomere recombination and is essential for repressing homology-directed repair (HDR), which can affect telomere length. Does not bind DNA directly: recruited to telomeric double-stranded 5'-TTAGGG-3' repeats via its interaction with TERF2. Independently of its function in telomeres, also acts as a transcription regulator: recruited to extratelomeric 5'-TTAGGG-3' sites via its association with TERF2 or other factors, and regulates gene expression. When cytoplasmic, associates with the I-kappa-B-kinase (IKK) complex and acts as a regulator of the NF-kappa-B signaling by promoting IKK-mediated phosphorylation of RELA/p65, leading to activate expression of NF-kappa-B target genes.
Synonyms: DRIP5; RAP1; LOC105371348
Tractability: PROTAC: UniProt records ubiquitination sites on it; ubiquitination databases record sites on it; its protein half-life has been measured; a small molecule that binds it is known.
Gene: Protein-coding gene on chromosome 16 (75,647,765 to 75,761,872, forward strand). Ensembl gene ENSG00000166848.
Subcellular location: Nucleus; Cytoplasm; Chromosome; Chromosome, telomere
Subcellular location (Human Protein Atlas): Nuclear bodies; Nucleoplasm
Pathways (Reactome):
Cell Cycle: Inhibition of DNA recombination at telomere; Packaging Of Telomere Ends; Polymerase switching on the C-strand of the telomere; Processive synthesis on the C-strand of the telomere; Removal of the Flap Intermediate from the C-strand; Telomere C-strand (Lagging Strand) Synthesis; Telomere C-strand synthesis initiation; Telomere Extension By Telomerase
DNA Repair: Cleavage of the damaged purine; Cleavage of the damaged pyrimidine; Recognition and association of DNA glycosylase with site containing an affected purine; Recognition and association of DNA glycosylase with site containing an affected pyrimidine
Cellular responses to stimuli: DNA Damage/Telomere Stress Induced Senescence
Reproduction: Meiotic synapsis
Gene Ontology:
Molecular function: G-rich strand telomeric DNA binding; phosphatase binding; protein binding; telomeric DNA binding
Biological process: intracellular signal transduction; negative regulation of telomere maintenance; protection from non-homologous end joining at telomere; protein localization to chromosome, telomeric region; regulation of telomere maintenance; telomere capping; telomere maintenance; negative regulation of DNA recombination at telomere; positive regulation of canonical NF-kappaB signal transduction; positive regulation of telomere maintenance; regulation of DNA-templated transcription; regulation of double-strand break repair via homologous recombination; telomere maintenance via telomerase; telomere maintenance via telomere lengthening
Cellular component: chromosome, telomeric region; cytoplasm; nuclear telomere cap complex; nucleus; shelterin complex; chromosome; nuclear chromosome; nucleoplasm
Genetic constraint (gnomAD): Loss-of-function variants: 35 observed, 32 expected, observed/expected ratio (o/e) 1.09, 90% interval 0.83 to 1.45. The upper end of that interval is the gene's LOEUF score, 1.45, which puts it in group 5 of 6, group 1 being the genes least tolerant of losing a copy. Missense variants: 583 observed, 509.01 expected, observed/expected ratio (o/e) 1.15, 90% interval 1.07 to 1.23. Synonymous variants: 253 observed, 215.5 expected, observed/expected ratio (o/e) 1.17, 90% interval 1.06 to 1.3.
Homologues: Orthologues: chimpanzee TERF2IP (99% identical), macaque TERF2IP (99% identical), dog TERF2IP (92% identical), pig TERF2IP (92% identical), rabbit TERF2IP (90% identical), mouse Terf2ip (85% identical), rat Terf2ip (84% identical), guinea pig TERF2IP (83% identical), tropical clawed frog terf2ip (38% identical), zebrafish terf2ip (32% identical).